BAP1 (BRCA1 associated deubiquitinase 1)
Diseases named in the same sentence as BAP1 in open-access papers (continued):
Sharing a sentence is not in itself a finding about the gene and the disease.
tumor (continued). "Indeed, patients who are affected by one BAP1-related malignancy are at increased risk of developing other cancers belonging to the BAP1-TPDS spectrum, and early tumor detection may allow a more effective management of such tumors." (PMID 35885614, 2022). "However, compared with vector control group, there were significantly fewer tumor cells disseminated away from the yolk sac in the Mel202 BAP1 KO cells, indicating the inhibitory effect of BAP1 deletion on invasion in Mel202 cells, which have SF3B1 mutation, but not OMM2.3 cells." (PMID 34706158, 2022). "Thus, it is possible that other genetic or epigenetic alterations might help cells bypass senescence associated with the combined mutations of BAP1 and SF3B1, leading to the co‐existing mutations of these two genes in rare tumor cases." (PMID 34706158, 2022). "In addition, sarcomatoid tumor cells in biphasic MPM can retain nuclear expression of BAP1." (PMID 35205798, 2022). "The clinicopathological characteristics (such as the diameter of the basal tumor, ciliary body involvement, and scleral expansion), non-random chromosomal aberrations, gene mutations (such as BAP1 and SF3B1 mutations) are considered to be related to the prognosis of patients with UM." (PMID 34630418, 2021). "As we found a positive association between LAG3 expression and its ligands and confirmed the association between LAG3 and loss of BAP1 expression/the presence of monosomy 3, we wondered whether expression of LAG3 ligands would similarly show associations with high-risk tumour characteristics." (PMID 34503258, 2021). "The mechanisms resulting in the distinct outcomes of BAP1 loss on the myeloid and lymphoid cell lineages merit further investigation, and may provide insights into the functions of BAP1 and its ASXL binding partners as tumor suppressors." (PMID 33912157, 2021). "BAP1 also binds the epigenetic scaffolding proteins additional sex combs-like-1/2/3 (ASXL1/2/3) to form the polycomb repressive deubiquitinase (PR-DUB) complex that exerts an essential tumour suppressor activity by regulating ubiquitination levels of histone H2A (H2AK119Ub)." (PMID 34170818, 2021). "Thus, the requirements of the tumor microenvironment could explain the delay between the origination of the BAP1 mutant clone, the BAP1-GPCR double mutant clone, and micrometastatic spread." (PMID 33903674, 2021). "In addition, the translocation of BAP1 was observed during tumor progression." (PMID 33155366, 2021). "Similarly to other tumor suppressor genes, the affected subjects inherit a non-functional BAP1 allele, whereas inactivation of the second allele occurs later in life." (PMID 33802313, 2021). "Notably, restoring PTEN expression could completely reverse the tumor‐promoting effect of BAP1 knockdown in vivo." (PMID 33155366, 2021). "Numerically longer OS in BAP1-altered MPM may reflect favorable tumor biology." (PMID 33777745, 2021). "BAP1 gene mutations have a strong association with an absent BAP1 protein expression, and in addition, the lack of protein expression and mislocalized protein expression result in tumor progression, the appearance of metastasis, and reduced rates of survival." (PMID 34771510, 2021). "Thus, BAP1-null tumor cells are more sensitive to EZH2 inhibitor treatment in vivo." (PMID 33483476, 2021).
tumor (continued). "Notably, a high prevalence of KDM5C and BAP1 alterations was identified in both the primary tumor and VTT tissues from ccRCC patients with VTT in our cohort (KDM5C: 21.74, 24.00, 4.00, and 7.00%; BAP1 30.43, 24.00, 4.00, and 10.00% for V, VP, NP, and TCGA, respectively)." (PMID 34249685, 2021). "The precise BAP1 tumor-suppressive mechanism remains unclear." (PMID 34186021, 2021). "With regard to the tumour, this contained a pathogenic somatic neurofibromatosis 2 (NF2) frameshift mutation and pathogenic loss of function somatic BAP1 mutation, which is in line with the immunohistochemistry result showing loss of nuclear labelling for BAP1." (PMID 34948918, 2021). "Current therapeutic approaches for BAP1-deficient tumours are not particularly promising." (PMID 33240524, 2020). "However, challenges will be faced due to tumor size and the heterogeneity in affected genes, especially the nonhotspot mutations that occur in BAP1." (PMID 33396957, 2020). "However, BAP1 mutation status alone did not significantly affect survival in this cohort and removal of all BAP1 mutant tumours from the cohort did not alter the correlation of HIF1A loss with poor prognosis." (PMID 32807776, 2020). "Since ISGF3 is activated by HIF and suppressed after the loss of PBRM1, KDM5C, SETD2 or BAP1, it may function as the executioner of a negative feedback loop that potently opposes tumor growth." (PMID 30355451, 2018). "Remarkably, rTRAIL treatment of tumour explants derived from three patients with MM also revealed increased levels of apoptosis (as measured by poly (ADP-ribose) polymerase (PARP) cleavage) in explants with low BAP1 expression compared with those with high BAP1 expression." (PMID 29345617, 2018). "The value of retrospective analysis of clinical trials based on the genomic landscape has clearly been demonstrated in the past and we wait with interest whether this will be performed on archived tumour tissue, in the context of BAP1 status, from previous trials." (PMID 29345617, 2018). "Therefore, we proposed that BAP1 is a putative tumor suppressor in ICC, and may serve as a valuable prognostic biomarker as well as a potential therapeutic target in ICC." (PMID 30305612, 2018). "Therefore, we hypothesised that somatically altered BAP1 might serve as a critical ingredient contributing to the PD-L1 expression in ccRCC tumor cells, and most likely work in concert with PD-L1 in tumor cells contributing to the aggressiveness of ccRCC." (PMID 30349421, 2018). "However, somatic BAP1 mutations have also been found and initialized in the neoplasm of sporadic MM, which does not always cause the loss of IHC staining." (PMID 28978163, 2017). "PBRM1, SETD2 and BAP1, similarly to VHL, map to the 3p21 and this suggests that essential component of ccRCC pathogenesis may be allelic loss of 3p resulting in haploinsufficiency for four tumor suppressors simultaneously." (PMID 28212566, 2017). "Also, the loss of BAP1 could regulate class I HDAC expression and affect the sensitivity of tumor cells to HDAC inhibitors." (PMID 28404968, 2017). "Our model identified mutations in VHL (von Hippel-Lindau), PBMR1, BAP1, MTOR, ATM, SETD2, KDM5C and PTEN (phosphatase and tensin homolog), as well as copy number changes in MLH1, DUSP1 and RANDBP17 as significantly associated with various TF activity changes across tumours." (PMID 28139702, 2017). "Additionally, BAP1 overexpression attenuated the promotive effect of miR-31 on tumor growth, suggesting that miR-31 might promote tumor growth by silencing BAP1." (PMID 26885612, 2016). "With progress in understanding the molecular landscape of the tumor and the development of treatments targeting the pathways involving GNAQ/GNA11, BAP1, EIF1AX, SF3B1 mutations and epigenetic mechanisms, in the near future it may be possible to prevent the progression of micrometastases." (PMID 27800275, 2016).
tumor (continued). "This binary approach to BAP1 immunohistochemistry assessment is the dominant approach used by surgical pathologists in routine clinical practice and has shown both excellent interobserver concordance and to correlate very well with molecular testing in a variety of tumour types." (PMID 26982343, 2016). "For sporadic MM patients with no obvious clinical treatment, the tumor-specific neo-antigen caused by frameshift mutations of Bap1 could be identified based on patient’s sequencing results and the prediction of its MHC-binding ability." (PMID 27187383, 2016). "Recently, a deubiquitinating enzyme, BAP1, with a role in cell cycle regulation was described as tumor suppressor, supporting the relevance of finding the corresponding GO category among the top 15 altered functions despite a moderate enrichment P-value in the tumor gene set (P<0.0001)." (PMID 21464922, 2011). "Specifically, BAP1 typically promotes the activation of IFNβ and STING mediated by HIF-2α, which helps inhibit tumor growth through the activation of interferon stimulated gene factor 3 (ISGF3)." (PMID 41602827, 2026). "Initial studies suggested that BAP1 primarily localizes to the nucleus, where it interacts with BRCA1 to enhance its tumor-suppressive function." (PMID 40918144, 2025). "When BAP1 expression is lost or reduced, PTEN becomes increasingly ubiquitinated and degraded, leading to unchecked cell proliferation and tumor progression by PI3K/AKT pathway activation." (PMID 40136571, 2025). "Low BAP1 leads to the accumulation of H2A ubiquitination, reinforcing the PRC1-mediated repression of tumor suppressor genes, thus creating a permissive environment for ERG overexpression and tumor progression." (PMID 40136571, 2025). "The scientific world is grappling with BAP1, MTAP, and the tumour inflammatory microenvironment, because they are the key for personalized treatments and palliative care in this disease." (PMID 40506895, 2025). "Disruption of the BAP1/IRF1/CIITA axis leads to a functional attenuation of MHC-II expression and MHC-II–dependent immune cell infiltration, leading to accelerated tumor growth in immunocompetent mice." (PMID 39817454, 2025). "Our previous studies have confirmed that BAP1 represses SLC7A11-mediated cystine metabolism and promotes ferroptosis-dependent tumor suppression." (PMID 41310183, 2025). "Furthermore, we highlight recent advances in identifying predictive biomarkers—such as genetic mutations (e.g., BAP1, MBD4), immune gene signatures, circulating tumor DNA, and protein-based blood markers—that may facilitate patient stratification and treatment selection." (PMID 40661151, 2025). "Emerging research on epigenetic alterations (BAP1, PBRM1, SETD2, CDKN2A) and tumor-stroma interactions is identifying new drug targets, including DNA damage response and CDK4/6 inhibitors, as well as microenvironment-directed therapies such as CSF1R blockade." (PMID 41426798, 2025). "The genes BAP1 and PBRM1 expression on the 3p chromosome are mentioned as being frequently deleted in ccRCC and as an independent predictor of tumor recurrence." (PMID 41479787, 2025). "The aim of this study is to investigate the role of BAP1, WT1, calretinin expression and their combinations in tumor tissue samples by IHC staining in predicting response and prognosis in PM patients treated with chemotherapy alone." (PMID 38280040, 2024).
tumor (continued). "BAP1 and PBRM1 gene expression, both on chromosome 3p, independently predict tumor recurrence, with BAP1-mutant tumors indicating worse outcomes." (PMID 38730649, 2024). "BAP1 was initially shown in cell nucleus where its primary interaction was binding to the BRCA1 and enhancing its tumor suppressive activity." (PMID 38175637, 2024). "We observed significantly greater tumor infiltration by cytotoxic T cells and DCs in MPM and MPeM tumors with BAP1-low expression." (PMID 38994676, 2024). "The most highly altered cancer types for BAP1 are KIRC, CHOL, UVM, MESO, LUSC and HNSC—all with >30% altered samples within their tumor types." (PMID 39554490, 2024). "Thanks to the increased availability of large gene panels for tumor next generation sequencing (NGS) in clinical practice, the identification of BAP1 carriers is expected to increase." (PMID 38673021, 2024). "The most common gene alterations in the primary tumor in RCC are VHL (64%), PBRM1 (36%), SETD2 (20%), and BAP1 (13%)." (PMID 38386122, 2024). "Alterations in BAP1, PBRM1, and SETD2 are common and important co‐driving factors in tumor development." (PMID 39166457, 2024). "To further investigate the relationship between BAP1 expression and the TIME, we assessed pairwise contacts between various immune cell types and tumor cells from malignant mesothelioma tumors with BAP1-high and BAP1-low expression levels." (PMID 38994676, 2024). "Further analysis of individual spots revealed a significant positive correlation between tumor infiltration by NK cells (CD56+) and average BAP1, NF2, MTAP, and LAG3 expression levels in MPM (ρ > 0.4)." (PMID 38994676, 2024). "The aim of this study is to investigate the predictive and prognostic role of BAP1, WT1 and calretinin expression and their combinations in pre-treatment tumor samples by immunohistochemical (IHC) staining." (PMID 38280040, 2024). "Unexpectedly, experiments with BAP1-depleted cell lines 92-1 and OCM1A injected into NOD-SCID-gamma mice showed less primary tumor growth in the flanks and less metastasis to the liver and lungs after injection into the tail veins." (PMID 39056751, 2024). "To investigate the clinical outcome, we conducted additional molecular analyses of the MPM tumor and we reviewed the literature on immunotherapy in MPM to discuss the role of PD-L1 and BAP1." (PMID 39091916, 2024). "Studies have found that SLC7A11 is a key target gene of BAP1, and BAP1 inhibits the expression of SLC7A11 by reducing H2Aub on the SLC7A11 promoter, promoting the occurrence of ferroptosis, and then inhibiting tumor growth." (PMID 36874967, 2023). "Importantly, recent developed BAP1 inhibitor iBAP-II could significantly reduce the small cell lung cancer (SCLC) cell viability and suppress tumor growth in vivo which proved an evidence for the oncogenic function of BAP1 and blocking BAP1 activity could be a novel therapeutic strategy." (PMID 37543638, 2023). "Consistent with in vitro cellular results, depletion of BAP1 significantly retarded the growth of tumor xenografts, whereas overexpression of MYCN partially rescued BAP1 depletion-mediated cells growth inhibition." (PMID 37543638, 2023). "To understand the impact of BAP1 deficiency on chromatin accessibility, we used snATAC-seq data to analyze differentially accessible chromatin regions (DACRs) by comparing the tumor cells of BAP1-mutants versus tumor cells from tumors without PBRM1 or BAP1 mutations." (PMID 36973268, 2023).
tumor (continued). "A recently accepted notion of RCC progression is that VHL mutation function as an initial event to drive tumorigenesis, while PBRM1, BAP1 and SETD2 subsequent trigger defects in DNA repair system and abnormal tumor growth." (PMID 37064095, 2023). "This is reasonable given that this chromosome contains four tumor-suppressor genes (VHL, PBRM1, BAP1, and SETD2) that are crucial for cellular survival." (PMID 37842234, 2023). "Four tumor suppressor genes map in this region: VHL in 3p.25, PBRM1 (subunit of the PBAF SWI/SNF chromatin remodeling complex), BAP1 (histone deubiquitinase), and SETD2 (histone methyl transferase) in 3p.21." (PMID 36902045, 2023). "Recent molecular biological studies have revealed frequent genetic alterations in three tumor suppressor genes, neurofibromatosis 2 (NF2), cyclin-dependent kinase inhibitor 2 A (CDKN2A, p16), and BAP1 in MMe." (PMID 37479714, 2023). "Tumor suppressors such as NF2 suppress ferroptosis, whereas other suppressors such as MLL4 FBW7, and BAP1 promote ferroptosis." (PMID 37580393, 2023). "Moreover, BAP1-KO had a negligible effect on cell proliferation, whereas CAMK2D/BAP1-DKO reduced cell proliferation, suggesting that an emerging BAP1-CAMK2D axis might play a critical role in the tumor growth of BAP1-deficient MMe cells." (PMID 37479714, 2023). "BAP1 was discovered during a protein interaction screening for BRCA1 and has been shown to collaborate with BRCA1 in tumor suppression in cultured cells." (PMID 36765733, 2023). "Comparing scRNA-seq data for BAP1 from wild and mutant type UM samples, researchers also reported that the upregulation of CADMS predominantly occurs in UM tumor cells." (PMID 37359513, 2023). "Initially we tested the anti-tumor efficacy of MLN4924, alone or combined with cisplatin, in 6 patient-derived MPM cultures, including all subtypes and BAP1+/BAP1- combinations." (PMID 35197103, 2022). "Alterations of BAP1 (70 %), CDKN2A (96 %), and NF2 (67 %) were detected at a higher frequency than reported for tumor biopsies." (PMID 36077838, 2022). "We have demonstrated that BAP1 directly binds to, deubiquitinates, and stabilizes KEAP1, exerting tumor suppressive effects in vitro." (PMID 35052618, 2022). "We found remarkable concordance in the protein expression of several key markers (BAP1, WT1, mesothelin, PD-L1, and VISTA) between the primary tumor and PDX tumors." (PMID 36380343, 2022). "3, primary tumor) and UM22 (mutant GNAQ and BAP1, metastasis) were treated with the HDACi entinostat and analyzed by flow cytometry." (PMID 34753889, 2022). "In humans, the VHL gene is located next to other tumor suppressors (e.g., PBRM1, BAP1 and SETD2) on chromosome 3p." (PMID 35463327, 2022). "We showed that by calculating the median transcription values of the four ccRCC tumour suppressors of 3p25 and 3p21 chromosomal loci—VHL, SETD2, PBRM1, and BAP1–, complemented that of the p14ARF, normal and ccRCC tissues can be distinguished." (PMID 35586183, 2022). "Genomic comparisons of these subtypes do not reveal mutually exclusive somatic alterations, with all harbouring, to some extent, the three most common tumour suppressors at 9p21.3 (CDKN2A), 3p21 (BAP1), or 22q (NF2)." (PMID 34067960, 2021). "Such dependency is preserved in BAP1 null cancer models addicted to hyper-H2AK119ub1 accumulation, making PCGF3/5-containing vPRC1 complexes attractive targets for these tumor types." (PMID 34186021, 2021). "Tumor suppressors such as PTEN, BAP1, and PML have been shown to induce apoptosis in cancer cell by promoting IP3R3-mediated Ca2+ flux from the ER to mitochondria." (PMID 34518526, 2021). "BAP1 induces ferroptosis by inhibiting cystine uptake and glutathione synthesis based on SLC7A11 inhibition, thereby inhibiting tumor development." (PMID 34616431, 2021).